FN1 (fibronectin 1)
Diseases named in the same sentence as FN1 in open-access papers (continued):
Sharing a sentence is not in itself a finding about the gene and the disease.
tumor (continued). "We performed enrichment pathway analyses to examine the role of C3 FN1+ TCs in tumor regeneration and to understand the specific functional activities of these cells during early developmental stages." (PMID 40612060, 2025). "The results showed that FN1 was significantly upregulated in TNBC tumor tissues and MDA-MB-231 cells compared to adjacent normal tissues and normal breast epithelial cells, as confirmed by RT-qPCR (P < 0.05) and IHC." (PMID 40438115, 2025). "Consistently, these top-weighted components of CPLF upregulated fibronectin 1 (FN1) expression in myofibroblasts, thereby activating integrin signaling in cancer cells and enhancing tumour progression." (PMID 41405822, 2025). "In conclusion, FN1 expression has significant prognostic value in PTC; the integrin–FN interaction plays a crucial biological role in this tumor and represents a potential target for targeted therapy." (PMID 40423510, 2025). "We found that in both metabolism-related pathways, SLC5A3 + tumor cells exhibit significant communication with CAFs, particularly through the FN1/SDC2, FGF7/FGFR1, NGF/SORT1, and LRPAP1/LRP1 receptor-ligand pairs." (PMID 40652057, 2025). "Ultimately, in vitro assays for functional confirmation demonstrated that FN1 knockdown diminished tumor cell invasiveness and activity." (PMID 40612060, 2025). "In comparison to vascular EC-specific expression in the grade III tumor, there was markedly elevated FN1 mRNA abundance in ECs and perivascular cells in the GBM sample." (PMID 41366031, 2025). "Based on our findings, we conclude that myofibroblast-derived CRC, TNS1, and FERMT2 orchestrate tumour progression by upregulating FN1, which subsequently activates integrin and FAK signaling in cancer cells." (PMID 41405822, 2025). "In vivo experiments also verified that Sch B inhibited HCC growth and downregulated the expression of FN1 protein in tumor tissues." (PMID 40223922, 2025). "It includes high expression of SPP1 and FN1, two genes that are recognized for their roles in promoting matrix remodeling and tumor invasion." (PMID 41397026, 2025). "Consistently, the number of lung metastasis tumours was significantly elevated in the FN1‐overexpressing group compared with the control group, which was partially restored by the FN1‐overexpressing and RAP1B‐silenced groups." (PMID 40638546, 2025). "Of note, in both cases tumor-bearing bones displayed upregulated Col1a1 and Fn1 levels compared with non-tumor-bearing bones, suggesting that differential response is due to intrinsic characteristics of each model, possibly influenced by AR signaling status." (PMID 40753365, 2025). "FN1 is an essential extracellular matrix element that facilitates tumour cell adhesion, motility, and metastasis." (PMID 40475773, 2025). "The role of FAP extends beyond molecular interactions influencing broader tumor behaviors and microenvironmental interactions by its enzymatic cleavage of FN1, which affects the availability and activation of TGF-β." (PMID 41233863, 2025). "As a key hub, the FN1 signaling pathway not only bridges physical and functional intercellular interactions but also drives metabolic adaptation to maintain tumor microenvironment homeostasis and immune dysfunction." (PMID 40380260, 2025). "The FN1 signalling pathway was upregulated in tumor samples and was widely present in ligand-receptor interactions in various cell types." (PMID 41181151, 2025). "We elucidate a novel mechanism whereby CPLF orchestrates myofibroblast–cancer cell crosstalk via the FN1/ILK/FAK pathway to drive tumour progression." (PMID 41405822, 2025). "While the presence of FN1 in the ECM has been shown to promote tumor progression and formation of metastasis by activating pro-proliferative signals in certain cancers, it is paradoxically associated with a better prognosis." (PMID 41488007, 2025).
tumor (continued). "We analyzed the correlation of FN1, ITGA4, ITGA5, ITGAV, ITGB1, ITGB3 and ITGB6 with disease status, risk of tumor recurrence according to the 2015 American Thyroid Association guidelines, and patient outcome." (PMID 40423510, 2025). "Although the precise mechanisms underlying FN1-mediated tumorigenesis in CRC remain to be fully elucidated, its upregulation has been shown to promote tumour growth and confer drug resistance in CRC (Ye, Zhang & Feng, 2020)." (PMID 40860666, 2025). "The expression of FN1 was validated highly expressed most in metastatic tumour tissues and much more highly expressed in primary tumour tissues compared to normal tissues from the TCGA dataset." (PMID 40638546, 2025). "FN1 is a glycoprotein that plays a role in the adhesion and migration of cells and it has also been shown to promote tumor growth, metastasis, and chemoresistance in the tumor microenvironment." (PMID 40096084, 2025). "Molecular analysis of the tumor via the TruSight-RNA-Fusion panel detected a fusion involving FN1::FGFR2, consistent with CCMN." (PMID 39404883, 2025). "In this context, our study focuses on FN1+ tumor cells using an integrated multi-omics approach, aiming to elucidate their role in immune escape and prognostic stratification." (PMID 40612060, 2025). "A similar pattern of gene expression persisted, where CA9 and VEGFA were upregulated within the in vivo RCC243 tumor models and ccRCC patient datasets, whereas FN1 was upregulated within cells grown in the in vitro RCC243 cell culture model." (PMID 40241258, 2025). "As a key ECM component, FN1 promotes tumor-cell proliferation, invasion, and matrix remodeling, and its expression correlates with poor prognosis and immune cell infiltration across multiple cancers." (PMID 41514658, 2025). "Intersection analysis of these DEGs indicated that the expression of two DEGs (TIMP1, FN1) differed significantly among the three groups, showing an upward trend in expression levels with tumour progression." (PMID 40638546, 2025). "Since the role of FN1 is context- and tumor-dependent, further studies are necessary to investigate the signaling pathways and FN1 as a pharmacological target." (PMID 41488007, 2025). "Key pathways involved include MDK, PTN, SPP1, and FN1, all of which play central roles in immune regulation and tumor progression." (PMID 40837013, 2025). "These miRNAs also exhibited tumor-suppressive roles by negatively correlating with key oncogenes such as FN1 and MET." (PMID 40647442, 2025). "The results indicated a positive correlation between the expression of STAT3 and FN1 with angiogenesis, tumor inflammation, and epithelial-mesenchymal transition (EMT)." (PMID 40772037, 2025). "This study investigates the immunological and prognostic significance of FN1-expressing tumor cells using integrated multi-omics approaches." (PMID 40612060, 2025). "Focusing on FN1, a critical target gene, enabled the development of novel immunoprecision therapies aimed at halting tumor growth and enhancing patient prognosis." (PMID 40612060, 2025). "Cell-cell communication analysis highlighted myCAFs' role in signaling, potentially influencing tumor cells towards increased malignancy through collagen, laminin, and FN1 signaling networks." (PMID 40207217, 2025). "Non-coding RNAs reciprocally regulate FN1: tumor-suppressive hsa_circ_0050386 binds SRSF3 to block FN1 pre-mRNA splicing and suppress metastasis, while oncogenic Lnc-PDZD7-3 upregulates FN1 to enhance MMP2/9-mediated invasion." (PMID 41301482, 2025). "Experiments about TNBC indicated that W23–1006 covalently inhibits ALKBH5, increasing the m6A level of fibronectin 1 (FN1) mRNA, thereby reducing the expression of FN1 and bringing overall tumor suppression both in vivo and in vivo." (PMID 40823087, 2025).
tumor (continued). "Prior studies have demonstrated that SPP1 interacts with CD44 to promote tumour cell proliferation and metastasis, while FN1, through integrin‐mediated adhesion signalling, enhances cell survival and invasion and drives metastatic progression." (PMID 40988131, 2025). "Interactions with tissue stem cells through the Col1a1/Cd93, Col1a1/Itga5, Fn1/Plaur and Itgb1/Vcan pathways underscore the critical role of the monocyte-macrophage system in tumour immunosurveillance and immunomodulation." (PMID 40046334, 2025). "Based on the significance of FN1 in the ECM formation, its association with stroma and the enzymatic activity of FAP on FN1, the TMA was stained for FAP and FN1 and their expression was evaluated in tumor (Tm) and connective tissues (CT)." (PMID 41233863, 2025). "Recent studies have also indicated that CAFs that overexpression of FN1 and periosteal protein can significantly promote the wound healing and invasion ability of tumor cells." (PMID 40626005, 2025). "Genes such as THY1, FN1, and BIRC5 function as diagnostic markers and demonstrate significant correlations with immune cell infiltration and tumour growth, indicating their dual involvement in disease identification and therapeutic intervention." (PMID 40475773, 2025). "The observed anti-invasive phenotype strongly suggests that miR-101-3p suppresses tumor progression through translational repression of FN-1, CXCL8, and/or other more dominant pro-metastatic factors." (PMID 41382114, 2025). "Spatial cell-cell communication networks further demonstrated that, compared to FN1− CAFs, FN1+ CAFs exhibited stronger spatial engagement with cytotoxic T cell subsets, including CTLs, across representative tumor sections." (PMID 41194113, 2025). "The levels of genes associated with tumor metastasis, including MAPK1, MAPK14, COL5A1, FN1, EP300, and FOSL2, were significantly downregulated after SH intervention." (PMID 41444284, 2025). "For both variants, rs78588384 within CNTN5 and rs200077102 within FN1, low MAFs, similar to the MAFs detected in PTC blood and tumor samples, were observed (p ≤ 0.001)." (PMID 39770638, 2024). "In summary, we demonstrate a connection between TGF-β, IL-6, TLR-2 and TLR-4 expression by the primary CRC tumor to SPP1 and FN1 expression in the metastatic intrahepatic tumor." (PMID 39372792, 2024). "Among the different ECM components, FN1 has been reported as a main driver of tumor progression by different mechanisms." (PMID 38546390, 2024). "FN1 activation contributes to tumor growth and progression by stimulating PI3K-AKT signaling, leading to enhanced cell survival, proliferation, and metastasis." (PMID 39065771, 2024). "ECM proteins produced by myCAFs, such as collagens, POSTN and FN1, interact with integrins on the surface of tumor cells, thereby activating Akt signaling." (PMID 38818409, 2024). "Further investigation showed that FN1 + TAMs were enriched in hypoxic tumor regions, implying that metabolic changes in tumors drive the production and recruitment of FN1 + TAMs." (PMID 39375795, 2024). "Concomitantly, ligands secreted by the AM macrophages, such as FN1, stimulate tumor growth by signaling via the START cell surface receptors." (PMID 38546390, 2024). "In an experimental mouse model of metastatic EOC, MS-275 limited tumor invasion, Fibronectin-1 secretion and the sub-mesothelial accumulation of MC-derived carcinoma-associated fibroblasts." (PMID 38254102, 2024). "Fibronectin 1 binds to cell surface receptors, mediating cross-talk between stromal and tumor cells, and interacting with integrin receptors to promote tumor progression by interfering with immune function or chemotherapy resistance." (PMID 39456895, 2024). "Fibronectin 1 (FN1) activated by activin A sustains SRC-mediated signaling in tumor cells, increasing proliferation." (PMID 39402303, 2024). "SNAI1, CDH1, and FN1 gene expression was detected more frequently in EPCAMlow than in EPCAM-negative primary tumor spots." (PMID 39456890, 2024).
tumor (continued). "We performed IHC with FN1 on xenograft tissues and the staining showed that the expression of FN1 was decreased in the tumor tissues overexpressing hsa_circ_0050386." (PMID 38216996, 2024). "Results from UALCAN indicate that FN1 expression levels are higher in various types of tumor tissues compared to adjacent tissues." (PMID 39684583, 2024). "C1QC+TAMs mostly receive CSF, CXCL, and MIF signals from CAFs, while SPP1+TAMs can communicate with CAFs through the pro-tumor FN1 or VEGF pathways." (PMID 39323622, 2024). "FN1 was identified to be specifically overexpressed in the tumor stroma and involved in the formation of a fibrous network suitable for tumor growth." (PMID 38898490, 2024). "In the tumor compartment, responders showed significant upregulation of genes encoding matrix metalloproteinase (MMP7) and FN1 proteins." (PMID 38378868, 2024). "In mouse models, NCR1-mediated IFN-γ production leads to increased expression of FN1 in tumors, thereby altering the primary tumor structure and reducing tumor metastasis." (PMID 38730335, 2024). "FAP+ mesenchymal cells play an important role in maintaining tumor‐permissive environment in various epithelial cancers, among others by depositing COLI and FN1, which promote tumor invasion." (PMID 38705944, 2024). "We underlined the value of CAFs in regulating tumor-promotion functions of myeloid cells through the production of MIF, CSF1, CXCL12, and FN1." (PMID 39323622, 2024). "Intriguingly, evidence suggests that FN1 serves as a direct transcriptional target of multiple miRNAs in tumors and circ0081534 has been pointed out to exert tumor oncogenic functions by manipulating the miR-508-5p/FN1 axis in NPC." (PMID 37056700, 2023). "FN1 protein expression was positively correlated with tumor size, T classification, N classification, and clinical stage (P < .001, P < .001, P = .002, and P < .001, respectively)." (PMID 37026938, 2023). "In light of FN1, recent studies demonstrated that increased FN1 secretion by PDAC stellate cells is correlated with aggressive tumor characteristics and promotes GEM resistance through the same ERK pathway." (PMID 37444617, 2023). "FN1 mRNA was significantly correlated with smoking index and FN1 protein was significantly correlated with tumor size." (PMID 37026938, 2023). "The other network included products of genes associated with tumour growth and cell proliferation (FN1, VEGFA), tumour progression and metastasis (CD44, ITGA2) and immune inhibition (NT5E)." (PMID 36649303, 2023). "Subcluster mFibro accounted for the majority of the fibroblast populations in tumor tissue and expressed a high level of COL1A1, MMP11, FN1 and POSTN, which were associated with collagen secretion and extracellular matrix modeling." (PMID 37265785, 2023). "Based on the previous significant differences in the expression levels of the two subtypes of C1 and C2 immune checkpoints, we further investigated the correlation between COL10A1/FAP/FN1 and tumor immune checkpoints." (PMID 38063927, 2023). "HNSCC is characterized by dysregulation of the autophagy–lysosome pathway, specifically the p62/SQSTM1 protein and overexpression of fibronectin 1 (FN1), which has been associated with poorer prognosis and higher tumor pathological grade in HNSCC patients." (PMID 37568764, 2023). "Of these, we selected the three genes with the highest transcript levels in 66cl4 CD45+ compared with CD45+ from 67NR tumours: Arg1, Fn1 and Thbs1." (PMID 37980483, 2023). "These FN1CAFs were capable of engaging with tumours by expressing ligands associated with EMT, including collagens, FN1 and LAMININ, primarily through collagens, FN1 and LAMININ interactions." (PMID 37784253, 2023). "Arginase 1 (Arg1) and fibronectin-1 (Fn1) are markers of immunosuppressive macrophages that potentiate tumor growth." (PMID 37461742, 2023). "Crucially, C3AR1 is positively correlated with 18 tumor metastasis related genes including FN1, SNAI2, and ZEB2." (PMID 37005667, 2023).
tumor (continued). "The major monocyte population in both metastasis and primary tumor was Mon Thbs1; however, metastasis had increased Mon Fn1 fraction and reduction in antigen-presenting Mon MHC-II." (PMID 37756565, 2023). "FN1 mRNA expression in ESCC tumor tissues was significantly higher than that in the corresponding normal esophageal tissues (P < .001)." (PMID 37026938, 2023). "The genes that showed increased expression in tumours were FN1, COL1A1 and MMP9 (p value < 0.05), which can be considered high-risk genes to indicate the prognosis level of patients with COAD." (PMID 37543674, 2023). "FN1 also limits tumour cell migration and promotes tumour metastasis by facilitating intercellular and cell matrix adhesion." (PMID 37640804, 2023). "We show that the presence of PRPF8 is instrumental for the inclusion (in other words, the reduced skipping) of FN1 exon 40.2, a cassette exon shown here to be more prevalent in tumor samples than in normal tissues in a wide variety of cancer types." (PMID 36609600, 2023). "We identified multiple clusters of mononuclear phagocytes including macrophages (Mac), several of which expressed genes associated with pro-tumour subtypes, including CD206 (Mrc1), Arg1, Retnla, Fn1 and C1qa50,51." (PMID 37605008, 2023). "The qRT-PCR results showed that the expression of FN1 mRNA was significantly higher in ESCC tumor tissues than in adjacent esophageal tissues (P < .01)." (PMID 37026938, 2023). "Along with Col1A1, a significant decrease of FN1 in viable tumor regions was detected with VEGF overexpression." (PMID 37389973, 2023). "Between these two genes, FN1, but not LAMB2, was expressed in a higher level in bone metastasis comparing to primary tumor and metastases in other organs using human datasets, suggesting a specific involvement of FN1 in bone-metastatic PC." (PMID 36749798, 2023). "Enhanced FN1 secretion is consistent with our previous study that showed more than fivefold increased expression of FN1 gene in RCC tumors as well as its correlation tumor grade and poor prognosis for patients." (PMID 37563650, 2023). "MYC has been deemed both a positive and negative regulator of YWHAB and FN1, hence depending on tissue and tumor type, the regulation of MYC varies." (PMID 37128318, 2023). "Overexpression of FN1 promotes tumour cell adhesion and aggregation through influencing tumour cell motility, differentiation, and proliferation." (PMID 37640804, 2023). "Consistency between the proteomics data and tumor gene expression was also reported for the upregulation of FN1 and the downregulation of CALR and AKAP12 in the HR-NB patients compared to the LR-NB cases." (PMID 37947594, 2023). "FN1 protein was expressed in tumor cells and stroma, localized in the membrane and cytoplasm of tumor cells." (PMID 37026938, 2023). "Together, these data indicated that macrophage-induced tumor cell FN1 expression significantly promoted anti-androgen resistance of bone-metastatic PC." (PMID 36749798, 2023). "L–R interaction analysis further allowed us to identify proximal enrichment of interactions involving Spp1 or Fn1, which were previously found to be associated with CRC tumor progression." (PMID 38012149, 2023). "FN1 levels were mildly correlated across the tumor pROIs and tROIs (Pearson’s r = 0.3548, p = 0.1485, adj." (PMID 37511126, 2023). "In particular, SNAI1 and FN1 were found to be positively correlated with EMT activation in more than half of the tumor types analyzed." (PMID 38144565, 2023). "Our research initially demonstrated the value of measuring the intensity of FN1 mRNA or FN1 protein expression in postoperative tumor specimens from patients with ESCC in determining the prognosis of patients." (PMID 37026938, 2023). "We then analyzed the correlation between COL10A1/FAP/FN1 and tumor immune cells, and the outcomes showed that FAP had significant positive correlations with macrophages, Th1 cells, neutrophils, iDC, Tgd, TReg, mast cells, and NK cells (R > 0.4, P < 0.001)." (PMID 38063927, 2023).